B2M (beta-2-microglobulin)
Diseases named in the same sentence as B2M in open-access papers (continued):
Sharing a sentence is not in itself a finding about the gene and the disease.
bladder cancer (11 papers, 2007 to 2024). "In accordance with our results B2M was found to be stably expressed in hypoxic cultured human chondrocytes and bladder cancer cells." (PMID 34035373, 2021). "A down-regulation of HLA-ABC and beta 2-microglobulin have been reported in microdissected tumor tissue derived from bladder carcinomas." (PMID 17980030, 2007). "B2M mutations are known to occur with varying frequencies in various tumor types and some tumors like bladder cancer are known to downregulate B2M in the absence of hard mutations within the gene." (PMID 38455061, 2024). "Additionally, they revealed that circ_0058063 increased the resistance of bladder cancer cells to cisplatin by sponging miR-335–5p to favorably regulate the expression of beta-2-microglobulin (B2M)." (PMID 39170516, 2024). "Taken together, our results demonstrated that circ_0058063 contributed to CDDP resistance of bladder cancer cells via sponging miR-335-5p, and B2M might be the downstream effector gene." (PMID 35321689, 2022). "Beta-2-microglobulin (B2M) is an MHC class 1 protein that was also identified as a cell surface protein on senescent EJ cells, a bladder cancer cell line following both p21 or p16 overexpression." (PMID 39578455, 2024). "According to geNorm software, two is the minimal number of reference genes, namely B2M and HRPT, for obtaining an accurate normalization under the hypoxic conditions in the studied cell bladder cancer lines." (PMID 27835695, 2016). "Accordingly, seven of the most commonly used reference genes (ACTB, GAPDH, HPRT, B2M, SDHA, TBP, and 18S) were amplified in the three bladder cancer cell lines exposed to normoxia and hypoxia." (PMID 27835695, 2016). "Accordingly, we have identified B2M and HPRT as the most stable reference genes to address the impact of oxygen shortage in hypoxic bladder cancer cells, irrespectively of their molecular nature." (PMID 27835695, 2016). "Tumor cell HLA-I expression was evaluated in 131 bladder cancer tissue samples using immunohistological staining with monoclonal antibodies against HLA-ABC, distinct locus-specific monomorphic determinants and against B2M." (PMID 34298868, 2021).
Alzheimer disease (10 papers, 2018 to 2025). A progressive, neurodegenerative disease characterized by loss of function and death of nerve cells in several areas of the brain leading to loss of cognitive function such as memory and language. "Currently, there was only one published study examining the association between B2M and Parkinson's disease, which reported a notably elevated B2M concentration in the CSF of Parkinson's patients, even surpassing that of Alzheimer's disease patients." (PMID 38743119, 2024). "The level of B2M is elevated in aging process, Alzheimer’s disease (AD) and HIV-associated dementia." (PMID 31708756, 2019). "Within the central nervous system, B2M is involved in the pathogenesis of diverse cerebral disorders, such as encephalopathy, Alzheimer’s disease, and cerebral tumors." (PMID 38836960, 2024). "For instance, studies of B2M in other neurodegenerative diseases other than Alzheimer's disease were limited." (PMID 38743119, 2024). "This study aims to analyze the link of plasma B2M to cerebrospinal fluid (CSF) Alzheimer’s disease (AD) biomarkers and cognition." (PMID 37005674, 2023). "Increased level of soluble B2M has been observed in the cerebral spinal fluid of patients with HIV-associated dementia, Parkinson’s diseases, and Alzheimer’s disease, as well as implicated in cognitive impairments related to chronic hemodialysis." (PMID 29795686, 2018). "In addition, increased level of soluble B2M has been observed in the cerebral spinal fluid of patients with HIV-associated dementia, Parkinson’s diseases and Alzheimer’s disease." (PMID 29795686, 2018).
renal dysfunction (10 papers, 2007 to 2026). "Notably, we observed that high serum levels of Gal-4 and Gal-7, along with moderate levels of Gal-1 (Cluster 3), were associated with renal dysfunction, as evidenced by elevated urea, creatinine, and beta-2 microglobulin levels." (PMID 39769262, 2024). "The reduction of serum B2M in patients with severe AIS may be related to the renal dysfunction associated with AIS." (PMID 37667193, 2023). "The associations between NT-proBNP and B2M, LDH, creatinine, and albumin imply a mechanistic link between inflammatory burden, renal dysfunction, and cardiac biomarker elevation." (PMID 41010591, 2025). "AUCs of ROC curves for NGAL/FuCr, CysC/FuCr and B2M/FuCr as predictors of renal dysfunction or death within 30 days after birth were: 0.793 (95% CI: 0.614-0.972, p = 0.001), 0.857 (95% CI: 0.7-1.0, p < 0.0001), 0.764 (95% CI: 0.562-0.966, p = 0.01), respectively." (PMID 41827472, 2026). "While early biomarkers of renal dysfunction like creatinine, cystatin c, and urinary beta-2 microglobulin are analyzed in other studies about renal T2* measurements, specific blood tests could not be performed in our study as it was designed retrospectively." (PMID 37065363, 2023). "In case of B2M gene, it has been recently shown that high levels of B2M protein in serum are associated with severity of coronary artery disease without renal dysfunction." (PMID 35439923, 2022). "Our study reveals a strong association between level of serum B2M and CAD (both prevalence and severity) in subjects without renal dysfunction." (PMID 28249620, 2017).
cognitive decline (9 papers, 2017 to 2025). "B2M in aging studies has been shown to induce microglial reactive responses and cause cognitive decline by increasing synaptic pruning and reducing neurogenesis." (PMID 39091874, 2024). "Given the association between cognitive decline and elevated B2M levels, as well as the role of Aβ pathology in mediating the impact of B2M on cognition, the potential role of B2M in the pathogenesis of AD appears to be substantiated." (PMID 37005674, 2023). "Considering the association between B2M levels and cognitive decline, B2M has been identified as a potential pro-aging factor which was implicated in age-related cognitive and regenerative impairments in the adult brain." (PMID 32059688, 2020). "This correlation highlights the potential of B2M as a biomarker for early detection and therapeutic intervention of aging-related cognitive decline." (PMID 40201544, 2025). "Cognition has been shown to be negatively regulated by B2M in both healthy ageing and in stages of cognitive decline, including dementia." (PMID 37438770, 2023). "Conversely, TLR4 KO can counteract the B2M-induced cognitive decline due to neuroinflammation and apoptosis via a modulation of hippocmapal neurogenesis, synaptic plasticity through TLR4/MyD88/NF-κB signaling pathway." (PMID 32059688, 2020). "Toll-like receptor 4 (TLR4) is a crucial receptor in neuroinflammation and apoptotic neuronal death, and increasing evidences indicated that β2-microglobulin (B2M) is thought to be a major contributor to age-related cognitive decline." (PMID 32059688, 2020). "Growing evidence links β2-microglobulin (B2M) to aging and cognitive decline." (PMID 40201544, 2025). "This implies that an increased B2M may induce the deposition of Aβ1–42, thereby leading to cognitive decline, as confirmed by our mediation analysis." (PMID 37005674, 2023). "In the present study, we found that B2M increased TLR4 mRNA expression in the hippocampus of WT mice for the first time, demonstrating TLR4 may be an important pathway for B2M to be a participant in age-related cognitive decline." (PMID 32059688, 2020). "Furthermore, exogenous B2M injection disrupts cognitive function and neurogenesis in young mice, but the lack of inherent B2M expression or the blockade of B2M function counteract cognitive decline associated with ageing and augments neurogenesis in aged mice." (PMID 40026116, 2025). "Interestingly, injecting B2m systemically or in the hippocampus impairs cognitive function and neurogenesis in young mice, and genetically knocking down B2m in aged mice abrogates age-related cognitive decline and enhances neurogenesis." (PMID 35980567, 2024). "The absence of endogenous B2M expression abrogates age-related cognitive decline and enhances neurogenesis in aged mice." (PMID 31643008, 2020). "It is also of interest to know if B2M accumulation is relevant to abnormalities in cerebral structure such as white matter hyperintensities and subcortical small-vessel disease, as commonly found in the elderly and CKD patients with cognitive decline." (PMID 31643008, 2020). "First, initiation of B2M treatment may represent a limitation because the half time of drugs, and measurement indicators levels were not fully rescued in TLR4 KO mice, other factors affected the B2M-induced cognitive decline should be researched in the future." (PMID 32059688, 2020).
dementia (9 papers, 2018 to 2025). Loss of intellectual abilities interfering with an individual's social and occupational functions. "This information is crucial to reveal the pathological mechanisms of B2M involvement in dementia or AD." (PMID 37005674, 2023). "Similar results were found in men, with B2M levels increasing with age and being higher in the dementia group compared to the healthy group." (PMID 37005674, 2023). "Additionally, an increase in B2M was detected in the cerebrospinal fluid of HIV-related dementia patients." (PMID 37005674, 2023). "Collectively, manipulations mitigating the effects of various pro‐ageing factors have been proposed as potentially effective approaches for slowing or reversing the ageing process and B2M may be one of these therapeutic targets for age‐related diseases, including sarcopenia and dementia." (PMID 40026116, 2025). "Clinical studies have reported that the level of B2M is elevated in cerebrospinal fluid of AD patients and HIV related dementia patients." (PMID 31708756, 2019).
graft versus host disease (9 papers, 2017 to 2025). An immune system disorder that occurs after allogeneic hematopoietic stem cell transplant and is a reaction of donor immune cells against host tissues. "Specifically, targeting B2M and TRAC aims to mitigate the risk of graft-versus-host disease by reducing the immune response when employing CAR-T cells from a healthy donor for patient treatment." (PMID 40027883, 2025). "Recent variants of these strains lacking MHC class I molecules (B2m) show increased CD4 to CD8 ratios and a longer time window before onset of xenogeneic graft versus host disease (GVHD) and represent improved strains for the study of human immune responses." (PMID 38900149, 2024). "This includes the design of universal CAR T cells with reduced potential for both initiating graft-versus-host disease (GVHD) and eliciting donor T-cell rejection, through targeted disruption of the endogenous T-cell receptor (TRAC) and beta-2 microglobulin (B2M), respectively." (PMID 31727131, 2019). "CRISPR/Cas9 has also been used to disrupt the TRAC and B2M genes to generate ‘universal’ allogeneic CAR T cells that knock out the endogenous TCR and HLA class-1 molecules, respectively, thereby limiting graft-versus-host-disease (GVHD) and immune rejection by T cells in patients." (PMID 38882639, 2024). "In agreement with previous studies, the lack of mouse MHC class I molecules in B2m-NOG mice, due to β2-microglobulin gene deletion (B2m), allowed preferential engraftment of CD4 T cells over CD8 T cells and delayed the onset of xenogeneic graft versus host disease (GVHD)." (PMID 40432752, 2025).
diffuse large B-cell lymphoma (8 papers, 2016 to 2024). "The prognostic value of serum beta-2 microglobulin for diffuse large B-cell lymphoma (DLBCL) is not well known in the rituximab era." (PMID 27764777, 2016). "B2m is also an important element in the immune escape mechanism since a decrease in b2m expression reduces the number of antigens presented on the cell surface, including tumor-related antigens, which has been shown in particular in diffuse large B-cell lymphoma." (PMID 36879200, 2023). "Robust evidence is available that correlates B2M variations and immune escape in CRC, and this gene also acts as a driver in diffuse large B cell lymphoma (DLBC)." (PMID 35751785, 2022). "In diffuse large B-cell lymphoma (DLBCL), alterations of B2M and CD58 show significant co-occurrence, acting synergistically on the immune escape mechanisms." (PMID 33918793, 2021).
Hodgkins lymphoma (8 papers, 2016 to 2024). A heterogeneous group of malignant lymphoid neoplasms of B-cell origin characterized histologically by the presence of Hodgkin and Reed-Sternberg (HRS) cells in the vast majority of cases. "Previous studies suggested serum beta-2 microglobulin level as a potential prognostic biomarker of diverse lymphoproliferative disorders, including Hodgkin lymphoma, mucosa-associated lymphoid tissue lymphoma, DLBCL prior to the rituximab era, mantle cell lymphoma, and nasal NK/T-cell lymphoma." (PMID 27764777, 2016). "Notably, truncating mutations of beta-2-microglobulin (B2M) were strongly associated with the nodular sclerosis subtype and younger age at diagnosis; however it remains controversial whether disruption of B2M/MHC class I expression leads to a better clinical outcome." (PMID 28893938, 2017). "The significance of serum beta-2 microglobulin (sβ2m) in Hodgkin lymphoma (HL) is controversial." (PMID 38254729, 2024). "In our study, genes related to major histocompatibility complex (MHC) class I and II machinery/biosynthesis such as HLA-DRA, CTSS, HLA-DPA1, HLA-DPB1, CTSC, B2M genes were expressed at higher levels in the mixed-cellularity subtype than in nodular sclerosis subtype at diagnosis." (PMID 36230815, 2022). "B cell (B2M) could potentially contributed to adult classical Hodgkin lymphoma, cutaneous T cell lymphoma, Ki1+ anaplastic large cell lymphoma and T cell leukemia." (PMID 34485161, 2021). "In patients with classical Hodgkin lymphoma, the SII was a better prognostic factor compared with the neutrophil-to-lymphocyte ratio, prognostic nutritional index, and beta-2-microglobulin (B2M)." (PMID 37909016, 2023).
Hypertension (8 papers, 2017 to 2025). The presence of chronic increased pressure in the systemic arterial system. "B2M, cystatin C and LCN-2 were all significantly associated with sex, overweight/obesity, hypertension, alcohol consumption and smoking." (PMID 37155257, 2023). "Elevated serum B2M, cystatin C, and LCN-2 levels were associated with being male, overweight/obesity, hypertension, alcohol consumption and smoking." (PMID 37155257, 2023). "Further, clinical predictors (heart failure, hypertension and heart rate (HR)) and biochemical risk factors (creatinine, BUN, UA, TG, TC, HDL-C, LDL-C, apolipoprotein-A, apolipoprotein-B, and B2M) were involved into multiple logistic regression model." (PMID 28249620, 2017). "This extends prior knowledge of the associations of SH2B324 and B2M25 with hypertension as we demonstrate a unidirectional causal association between SH2B3 expression and plasma B2M levels, and thus provide plausible evidence for a causal role of the SH2B3-B2M axis in hypertension." (PMID 30111768, 2018). "A 71-year-old female, with hypertension, depression, and asthma, was diagnosed with chronic lymphocytic leukemia (CLL) (elevated beta-2 microglobulin and deletion of 13 q chromosome) and treated with ibrutinib." (PMID 40276403, 2025).
kidney damage (8 papers, 2017 to 2025). "In type 2 diabetes, urinary B2M excretion has been associated with macrovascular disease and nephropathy." (PMID 30024955, 2018). "Other biomarkers potentially useful to indicate kidney damage are β2-Microglobulin (B2M) and Beta Trace Protein (BTP)." (PMID 37189669, 2023). "Our study supports existing literature in identifying higher levels of specific biomarkers of kidney damage (i. e., NGAL, OPN, and B2M) that are associated with shorter gestations as well as lower birth weights." (PMID 31891650, 2019). "This study investigates the clinical utility of urinary beta-2-microglobulin levels in detecting early nephropathy in African diabetics." (PMID 28250988, 2017). "This has led to the proposal to use a panel of urinary markers (including beta-2-microglobulin) to increase the chances of detecting early nephropathy in diabetics." (PMID 28250988, 2017). "Whether B2M does indeed surpass the novel kidney injury biomarkers in indicating kidney damage and what pathophysiologic differences and similarities exist remains to be studied." (PMID 38839764, 2024). "Thus, elevated levels of BTP and B2M in urine can be an indication of kidney damage or dysfunction, and can be used as biomarkers to diagnose and monitor various kidney-related diseases and conditions." (PMID 37189669, 2023). "From a large-sample size analysis, we discovered and validated 2 protein peaks, B2M (11.7 kDa) and CC16 (15.8 kDa), as biomarkers associated with nephropathy and verified the discriminatory ability in a set of 238 individuals including diabetic and nondiabetic patients." (PMID 30024955, 2018). "Promising biomarker candidates for kidney damage in Bothrops snakebites were retinol-binding protein (RBP4), beta-2-microglobulin (B2M), cystatin-C (CST3), hepcidin (HAMP), and fatty acid-binding protein (L-FABP)." (PMID 38536893, 2024). "The detection of B2M and CC16 with the C18 plate—MALDI-TOF MS approach could be an attractive and practical assay for rapid diagnosis of nephropathy in nondiabetic/diabetic patients and as a predictor of ERFD among T2D patients who had not manifested significant kidney disease at baseline." (PMID 30024955, 2018). "Therefore, we aimed to assess the pathophysiological properties of urinary B2M, TIMP-2, IGFBP7, KIM-1 and NGAL in a healthy cohort of living kidney donors before and after unilateral nephrectomy, to study the effect of a reduction in kidney mass rather than kidney damage." (PMID 38839764, 2024).
lung adenocarcinoma (8 papers, 2017 to 2025). A carcinoma that arises from the lung and is characterized by the presence of malignant glandular epithelial cells. "B2M shapes the immune landscape of lung adenocarcinoma and causes resistance to PD-1-based immunotherapy." (PMID 35903675, 2022). "One lung adenocarcinoma tumor had also acquired a mutation in β-2 microglobulin (B2m), which is vital for MHC class I expression and peptide binding stability." (PMID 29107330, 2017). "The copy numbers of both the target (CYP2C8, CYP3A4) and the reference genes (ALB, B2M, BCKDHA, F5, CD36, MPO, TBP, RPPH1) established in primary lung adenocarcinoma by the qPCR-based method were congruent with those determined by next-generation sequencing (for 10 genes, slope = 0.9498, r2 = 0.72)." (PMID 37686184, 2023).
renal carcinoma (8 papers, 2013 to 2024). A carcinoma arising from the epithelium of the renal parenchyma or the renal pelvis. "In addition, B2M overexpression has been shown to support bone metastasis in human prostate, breast, lung, and renal cancer cells via regulating the epithelial‐to‐mesenchymal transition of tumor cells." (PMID 33960680, 2021). "They compared the conformation and surface expression of free HLA-C1 HCs in the absence of B2m in the kidney carcinoma cell line KJ29, which carries two apparently normal copies of chromosome 6 and a single chromosome 15, implying the loss of one copy of the B2m gene." (PMID 37627243, 2023).